EHF (ETS homologous factor)
Diseases named in the same sentence as EHF in open-access papers (continued):
Sharing a sentence is not in itself a finding about the gene and the disease.
oral cancer (2 papers, 2019 to 2022). "In conclusion, we discovered a novel regulatory cascade of miR-365-3p/EHF/KRT16/β5-integrin/c-Met signaling regulating oral cancer metastasis, cancer stemness, and drug resistance." (PMID 30782177, 2019). "Transcriptome analysis suggested that miRNA-1307-5p could promote oral cancer progression by suppressing THOP1, EHF, RNF4, GET4 and RNF114." (PMID 36142544, 2022).
oral squamous cell carcinoma (2 papers, 2021 to 2022). "In addition, microRNA-365-3p targeted ETS homologous factor, a KRT16 transcription factor, to suppress migration, invasion, and metastasis in oral squamous cell carcinoma cells by suppressing KRT16." (PMID 35037835, 2022). "In the Cancer Genome Atlas (TCGA) dataset of four oral squamous cell carcinoma tissues, EHF mRNA levels were not correlated negatively with those of ETS1, while a weak negative correlation was detected only in the GSE37991 dataset." (PMID 33712555, 2021).
papillary thyroid cancers (2 papers, 2016 to 2018). "EHF mRNA and protein is expressed in papillary thyroid cancers (PTCs) and EHF knockdown in PTC cell lines inhibits cell proliferation, invasion and migration in vitro and in vivo." (PMID 30200227, 2018). "Using quantitative RT-PCR (qRT-PCR) assay, we evaluated mRNA expression of EHF in a cohort of primary papillary thyroid cancers (PTCs) and matched non-cancerous thyroid tissues." (PMID 27517321, 2016).
psoriasis (2 papers, 2015 to 2025). An autoimmune condition characterized by red, well-delineated plaques with silvery scales that are usually on the extensor surfaces and scalp. "Co‐expression analysis revealed a strong correlation between LINC01206 and EHF in psoriasis, suggesting their functional interaction." (PMID 40670887, 2025). "This regulatory circuit was experimentally validated in normal human epidermal keratinocytes (NHEK), highlighting the critical role of LINC01206 in psoriasis pathogenesis through its interaction with EHF and cell cycle genes." (PMID 40670887, 2025). "By regulating EHF and its downstream targets, LINC01206 emerges as a key player in psoriasis pathogenesis and a potential therapeutic target for future interventions." (PMID 40670887, 2025). "Although 106 TFs are encoded by psoriasis DEGs, only a fraction interacts with PREs (26/106), and several of these have not yet been examined in psoriasis studies (e.g., FOXM1, EHF, SOX5)." (PMID 25883770, 2015). "Through in silico screening of known DNA binding sites, our findings highlight proteins not yet well studied in psoriasis, including TFs (FOXM1, EHF, SOX5) and uDBPs (AVEN, RBM8A, GPAM, WISP2)." (PMID 25883770, 2015). "Additionally, however, we uncovered TFs not extensively studied in psoriasis, but which may nonetheless have important roles in KC differentiation, KC proliferation, apoptosis, inflammation, WNT signaling and lipid synthesis (e.g., FOXM1 and EHF)." (PMID 25883770, 2015).
triple-negative breast carcinoma (2 papers, 2023 to 2024). An invasive breast carcinoma which is negative for expression of estrogen receptor (ER), progesterone receptor (PR), and human epidermal growth factor receptor 2 (HER2). "Using overexpression and knockdown approaches, recent studies have shown that EHF has a tumor suppressor role in triple negative breast cancer cells via inhibition of epithelial-mesenchymal transition (EMT) and metastasis while sensitizing cells to chemotherapy and inducing apoptosis." (PMID 38317241, 2024). "We found that the tumor suppressor NDRG2 is correlated with EHF gene expression in triple-negative breast cancer cells, that EHF overexpression results in reduced cell proliferation and that apoptosis is promoted by the chemotherapeutic reagent treatment of EHF-overexpressing cells." (PMID 37958443, 2023).
adenoma (1 paper, 2020). A neoplasm arising from the epithelium. "For module yellow, which is progressively up-regulated from normal stroma to adenoma to mCA, the top candidate hub genes consisted of CDH1, ST14, EHF, KRT8, and KIAA1217, all of which have important roles in epithelial cells, and/or are associated with tumour malignancy." (PMID 32218455, 2020).
bladder cancer (1 paper, 2021). "Since the L329P mutation in ELF3 is deposited in the TCGA dataset for bladder cancer, the corresponding L285P mutation in EHF was further investigated." (PMID 33712555, 2021). "Occasional mutation and amplification of EHF occurs in a subset of cancers, such as ovarian, stomach, and bladder cancer." (PMID 33712555, 2021).
cervical cancer (1 paper, 2023). A primary or metastatic malignant neoplasm involving the cervix. "Additionally, cervical cancer patients with elevated expression of BNC1, EHF, and IRF6 have a decreased rate of survival relative to patients with low expression of these genes." (PMID 37627195, 2023).
cervical tumors (1 paper, 2020). "For example, although EHF and NEAT1 are known cytoplasmic targets of miR-365 regulation in oral caners, the potential for miR-365 to modulate other targets has been verified in additional cancers, such as breast skin, lung, liver, and cervical tumors." (PMID 32727045, 2020).
endometriosis (1 paper, 2025). The growth of functional endometrial tissue in anatomic sites outside the uterine body. "Moreover, the differences in EHF expression between normal endometrium and the endometrium of patients with endometriosis remain to be further explored." (PMID 40046872, 2025).
metastatic prostate carcinoma (1 paper, 2019). A carcinoma that arises from the prostate gland and has spread to other anatomic sites. "We observed that expression of ESE3/EHF and IL-6 were significantly anti-correlated in primary and metastatic prostate cancers." (PMID 31143708, 2019).
osteosarcoma (1 paper, 2023). A usually aggressive malignant bone-forming mesenchymal neoplasm, predominantly affecting adolescents and young adults.
thyroid (1 paper, 2016). "Importantly, EHF was identified as a new transcription factor for HER2 and HER3, contributing to thyroid tumorigenesis." (PMID 27517321, 2016).
tongue cancer (1 paper, 2021). A malignant neoplasm affecting the tongue. "Unfortunately, we could not detect the L285P mutation in EHF among 15 human patients with tongue cancer, though some mutations were found in the ESE domain." (PMID 33712555, 2021). "Immunohistochemical analysis was also performed using an anti-EHF antibody on specimens from human patients with tongue cancer after we characterized the specificity of the antibody using cells transfected with either siRNAs against EHF or plasmid encoding EHF-SF (data not shown)." (PMID 33712555, 2021). "We therefore investigated genomic alteration in the ESE domain of the EHF and ELF3 genes by sequencing, after genomic DNA was isolated from specimens of human patients with tongue cancer." (PMID 33712555, 2021).
tumor (42 papers, 2007 to 2025). "Specifically, authors found that new point mutations within the conserved ETS domain of EHF increase the tumour invasion in vivo by abolishing the native function of EHF protein." (PMID 35453848, 2022). "IHC of serial sections revealed that high expressions of CRC (ELF3/EHF/TGIF1-High) were closely associated with high proliferative activity in tumor tissue and poor prognosis on patients with LUAD." (PMID 33070167, 2020). "Loss of EHF expression is more pronounced in tumours with higher expression of cancer stem cell markers, and is associated with poorer patient outcome." (PMID 30200227, 2018). "Hence, EHF expression has also been associated with both tumour occurrence/progression and its inhibition." (PMID 35453848, 2022). "In particular, this included genes involved in secretory pathways, lipid and sugar metabolism (such as, UGDH, SORD, GLUD1, ELOVL5, ASCL3, UAP1), but also genes implicated in tumor progression and metastasis with functions in cell survival, proliferation and adhesion (EHF, ELL2, TPD52, MAFB, SGK)." (PMID 21829708, 2011). "The TCGA-derived RNA-seq profiles proved that EHF was highly expressed in tumor samples of LUAD and LUSC patients (P < 0.001, P < 0.001)." (PMID 41320721, 2025). "By utilizing CCK‐8 and colony formation assays, we found that EHF acted as a tumor‐suppressor, restraining RCC cell proliferation." (PMID 40411401, 2025). "Consistently, in vivo results from IHC staining for EHF in mouse lungs suggested that shJMJD6 A549 tumors had lower tumor expression of EHF." (PMID 41320721, 2025). "In WT tumor cells, regulons associated with NFKB1, XBP1, JUN, SREBF2, and EHF exhibited elevated activity." (PMID 40767963, 2025). "We validated that EHF promotes the migration and infiltration of TAMs into tumors through the CCL2/CCR2 axis, which complements the function of GLI1 in tumor cells and provides a more comprehensive mechanism for EHF‐mediated cholangiocarcinogenesis." (PMID 38741887, 2024). "Statistical analysis demonstrated a positive correlation between EHF expression and tumor size as well as TNM stage (p < 0.05)." (PMID 38741887, 2024). "We also examined some markers closely related to tumor cell proliferation, and the results showed that EHF promoted their expression in CCA cells." (PMID 38741887, 2024). "Collectively, these results demonstrated the tumor suppressive role of EHF by inhibiting growth and enhancing drug sensitivity in TNBC cells." (PMID 37958443, 2023). "In the case of RAB25 and EHF, both genes are well-known tumor suppressors that changed their methylation state." (PMID 37693315, 2023). "The subcutaneous injection of 4T1-EHF cells into Balb/c mice resulted in smaller tumor sizes compared to 4T1-mock tumors, and pulmonary metastasis was also suppressed by EHF overexpression." (PMID 37958443, 2023). "The EHF overexpression suppressed the migration of tumor cells, so the number of pulmonary nodules was significantly reduced compared to that in mock tumors." (PMID 37958443, 2023). "To further evaluate the role of EHF in tumor progression in vivo, we established a stable 4T1-EHF cell line." (PMID 37958443, 2023). "Taken together, the results show that EHF suppressed tumor progression by inducing cellular senescence in vivo." (PMID 37958443, 2023). "EHF is a transcription factor that plays a vital role in cell differentiation and tumour-initiating and metastatic capability by conferring a CSC-like phenotype." (PMID 36142544, 2022). "In follow up studies, we made further progress in understanding the tumor suppressor role of ESE3/EHF, particularly with respect to its function in cell differentiation and stemness." (PMID 31143708, 2019). "Several ETS family members have been shown to act as tumor suppressors within the prostate (EHF, SPDEF, ERF, etc)." (PMID 30603056, 2018). "The data presented here establish an additional mechanism by which ESE3/EHF restrains stemness and tumor progression through repression of IL-6." (PMID 27732936, 2016).
tumor (continued). "We recently reported a tumor suppressor role of ESE3/EHF in controlling differentiation and cancer stem-like phenotype in human prostate epithelial cells." (PMID 27732936, 2016). "Currently, the role of EHF in tumor progression has been relatively well-studied." (PMID 40046872, 2025). "Activation of the TGF-β/SMAD axis has long been recognized to facilitate the metastatic capacity of cancer cells, we next determined whether the inhibition of tumor metastasis by EHF knockdown was mediated by the TGF-β/SMAD signaling." (PMID 41320721, 2025). "In addition, GLI1 blockade effectively attenuated EHF upregulation in tumor cells and immunosuppressed animal models, thereby reducing CCA cell proliferation and growth." (PMID 38741887, 2024). "In addition, PC-derived extracellular vesicle (EV) miR-155-5p can promote tumor immune escape by targeting the tumor suppressor EHF to downregulate, and activate Akt/NF-κB signaling." (PMID 39555076, 2024). "Likewise, studies have found EHF to be an important tumor suppressor in the prostate and pancreas via promotion of differentiation and inhibition of EMT, which impedes metastasis and is rescued by re-expression of EHF." (PMID 38317241, 2024). "Furthermore, we performed immunohistochemistry (IHC) staining to assess the expression of EHF in tumor tissues from 137 patients with CCA." (PMID 38741887, 2024). "The correlation between EHF and NDRG2 led us to hypothesize that EHF may function as a tumor suppressor in TNBC cells." (PMID 37958443, 2023). "Next, we investigated whether the EHF overexpression in 4T1 cells affected splenomegaly induced by tumor cells." (PMID 37958443, 2023). "The overexpression of EHF also reduced the tumor size, and lung metastasis in vivo." (PMID 37958443, 2023). "Consistent with our cell line data, expression of EHF, as well as colonic differentiation markers, colonic stem cell markers and colon-specific transcription factors were significantly reduced in poorly-differentiated tumours." (PMID 35606410, 2022). "Loss of EHF expression induces epithelial–mesenchymal transition (EMT) and cell dedifferentiation, and confers to prostate epithelial cells a stem-like phenotype, along with aggressive and tumor-initiating properties." (PMID 33414441, 2021). "We confirmed that EHF repressed t-NEPC makers while inhibiting the tumor growth." (PMID 33414441, 2021). "We next investigated whether the EHF overexpression could inhibit tumor progression in vivo." (PMID 37958443, 2023). "Further elucidation of the signalling and transcriptional events which regulate EHF and CDX1 expression may therefore further unveil the hierarchy of differentiation loss in CRC, and uncover potential therapeutic strategies for CRC based on the re-induction of EHF/CDX1-driven tumour differentiation." (PMID 35606410, 2022). "Furthermore, we showed that ESE3/EHF controls the differentiation program of prostate epithelial cells and its loss alters cell differentiation and conferred a CSC-like phenotype along with tumor-initiating and metastatic capability." (PMID 27732936, 2016). "Bioinformatics analysis revealed that miR-1307-5p likely contributes to cancer progression by downregulating tumor-suppressive genes, such as THOP1, EHF, RNF4, GET4, and RNF114." (PMID 40699851, 2025). "Simultaneously, differentiation- and immune-activating signals such as CSF1, TNFSF9, KITLG, EHF, and CHRM1 were downregulated, potentially modulating tumor immune escape and proliferation in a context-dependent manner." (PMID 41009714, 2025). "Bioinformatics analysis suggested that miR-1307-5p promotes cancer progression by suppressing key tumor suppressor genes such as THOP1, EHF, RNF4, GET4, and RNF114." (PMID 40699851, 2025). "Expression of CCL28, APP, EHF and LINC00342, among others, is increased in LP cells relative to the basal tumor." (PMID 39478117, 2024).
tumor (continued). "Tumour infiltrating lymphocyte and myeloid populations were enriched for motifs including ETS family transcription factors (ETV5/6 and EHF) and MEF2B, as well as NFKB1 which is a central activator of pro-inflammatory genes." (PMID 39341888, 2024). "By contrast, inactivation of EHF and CDX1 in well-differentiated CRC cells triggered tumour de-differentiation." (PMID 35606410, 2022). "Taken together, these data indicate that EHF and CDX1 are critical regulators of CRC differentiation and suppressors of tumour progression." (PMID 35606410, 2022). "IHC revealed that expressions of ELF3, EHF and TGIF1 were higher in LUAD tumor tissues compared with peritumoral tissues." (PMID 33070167, 2020). "Remarkably, ELF3, EHF, and TGIF1 were highly expressed in LUAD tumor tissue compared with normal lung tissue, and the high expression of these TFs were positively correlated with poor prognosis in LUAD patients." (PMID 33070167, 2020). "While re-expression of EHF alone failed to re-induce differentiation of these tumours, combined re-expression of EHF and CDX1 re-induced expression of multiple enterocytic differentiation markers and gland formation, and inhibited tumour growth and metastasis." (PMID 35606410, 2022). "In this study, we discovered that the expression level of EHF was significantly higher in cancer tissues of patients with CCA than in adjacent noncancerous tissues, and that it was correlated with tumor size and TNM staging." (PMID 38741887, 2024). "Interestingly, when a proved NEPC driver gene SRRM412 was exogenously introduced into PCa cells, tumor cells almost without EHF expression, just like DU145 cells, could acquire a pluripotency gene network that could not be induced by SRRM4 in cells with EHF endogenous expression." (PMID 33414441, 2021).